ELK1 (ETS transcription factor ELK1)
Diseases named in the same sentence as ELK1 in open-access papers (continued):
Sharing a sentence is not in itself a finding about the gene and the disease.
tumor (continued). "Tumor volume analysis showed that tumors grew slower in ELK1-KD group than that in ELK1-KD/LGMN-OE group (*p < 0.001, **p < 0.001)." (PMID 34966781, 2021). "Functionally, we showed that the transgenic expression of Elk-1 in macrophages obviously enhanced Sirpα expression, potentiated tumor growth and shortened survival." (PMID 32296015, 2020). "In MC-38-based xenograft models, we confirmed that the binding activity of the Ap-2α protein and Elk-1 gene promoter in TAMs increased with tumor progression." (PMID 32296015, 2020). "Consistent with the expression profile of Sirpα, the mRNA levels of Elk-1 in TAMs increased with tumor progression in MC-38- and CT-26 cell-based subcutaneous tumor models and in spontaneous tumor models." (PMID 32296015, 2020). "As a key member of the Ets family and ternary complex factor (TCF) subfamily, ELK1 has influenced various steps of many tumor development largely through Ras-Raf-MAPK signaling cascade." (PMID 32275642, 2020). "In vivo phagocytosis assays showed that the myeloid-specific ablation of Ap2α induced tumor phagocytosis, and this effect was fully prevented by the expression of the Elk-1 transgene in macrophages." (PMID 32296015, 2020). "In mouse TAMs, we demonstrated that the binding of the Elk-1 protein and Sirpα DNA increased with tumor progression." (PMID 32296015, 2020). "The role of chemokines in tumor angiogenesis was achieved in a CCR7-dependent manner through inhibiting Met/ERK/Elk-1/HIF-1α/VEGF-A pathway in CRC." (PMID 31214045, 2019). "LncRNA-HOTAIR promotes cell growth and metastasis by inhibition miR-326 expression, whereas up-regulated miR-326 suppressed CC cell tumor tumorigenicity via targeting Elk-1." (PMID 31164797, 2019). "Specifically, NDUFA4L2 is overexpressed in clear cell RCC (ccRCC); its mRNA level is correlated with tumor stage and overall survival time; and the association of NDUFA4L2 with ccRCC is regulated by ELK1." (PMID 31046666, 2019). "While all of the tumor cells at both diagnosis and relapse shared the two SNVs in CREBBP and RGS11, five additional mutations in NRF1, MARCKS, USP11, ELK1, and MYC were detected at diagnosis." (PMID 26527318, 2016). "Our in vivo results also showed that afatinib downregulated CIP2A through Elk-1 in H358 xenograft tumors and inhibited tumor growth." (PMID 25537503, 2015). "In accordance with our in vitro findings, ELK1-shRNA expression considerably retarded tumor formation as well as its growth in xenograft-bearing male mice." (PMID 26342199, 2015). "We examined CIP2A and Elk-1 expressions in paraffin-embedded tumor tissues from patients who underwent surgical resection for NSCLC." (PMID 25537503, 2015). "P90RSK and Elk-1 are involved in tumor progression and biochemical changes in chromatin structure, and indirectly increasing cell proliferation through c-Fos activation, respectively." (PMID 25122124, 2014). "Circ-PTPDC1 acts as sponge of the tumor suppressor miR-139-3p, which is a micro-RNA targeting ELK1." (PMID 40862737, 2025). "Since PGE2 can promote BC tumorigenesis, the study concluded that 15 d-PGJ2 may activate ELK1, but instead of attributing ELK1’d expression with tumorigenic activity, its activation may result in tumor-suppressive effects." (PMID 40862737, 2025). "Besides EGR1, ELK1 has been reported to promote the activation of several other TFs, all credited with important roles— in various aspects of tumorigenesis, tumor progression and aggressivity." (PMID 40862737, 2025). "ELK1 has also been reported to be the target of micro-RNAs that act as tumor suppressors." (PMID 40862737, 2025). "Besides the cytoskeleton, ELK1 has also been found to affect tumor microenvironment in PaCa, through modulation of the cysteine protease Legumain (LGMN)." (PMID 40862737, 2025). "ELK1 has been studied in the context of memory, addiction, and neurogenerative diseases; however, studies implicating it in tumor-associated process are not rare." (PMID 40862737, 2025).
tumor (continued). "ELK1 targeting has been suggested as a way to suppress PaCa tumor growth and aggressiveness." (PMID 40862737, 2025). "Additionally, they credited ELK1 with roles regarding tumor microenvironment (TME) and evasion from the immune system, while also underscoring its high prognostic value." (PMID 40862737, 2025). "In addition, it has been reported that the expression level of ELK1 exhibited the positive correlation with tumor malignant progression, which was regulated by AS." (PMID 35832652, 2022). "In addition, we found that ELK1 expression was remarkably elevated in tumor tissues compared to adjacent normal tissues (P < 0.001)." (PMID 35123530, 2022). "Taken together, these data demonstrate that ELK1 promotes LUAD tumor growth in vivo." (PMID 34970415, 2021). "In contrast, in the mice administered with ELK1-overexpressing H460 cells, tumors developed faster compared to those in mice injected with the control, i.e., H460 cells (vector group), and exhibited higher tumor weights and larger tumor volumes." (PMID 34970415, 2021). "Furthermore, when endogenous ELK-1 was silenced in the primary tumor culture of patient 624 (middle level of ELK-1 expression), CD133, NANOG, SOX2, and POU5F1 levels were all downregulated as compared to scramble RNA control." (PMID 33672811, 2021). "Moreover, circPPFIA1 knockdown also inhibited the expression of ELK1 in tumor tissues, which further confirms the interaction between circPPFIA1 and ELK1." (PMID 34455918, 2021). "Furthermore, we revealed that miR-873 acted as a tumor-suppressive microRNA by directly binding to the 3ʹUTRs of ELK1 and STRN4 and suppressed their expression." (PMID 31289617, 2019). "Furthermore, we also revealed that CXCL5 secreted by tumor cells was able to promote CRC migration through ERK/Elk-1/Snail-mediated EMT (Epithelial mesenchymal transition) and invasion via the AKT/GSK3β/β-catenin/MMP7 pathway in a CXCR2-dependent manner." (PMID 28356111, 2017). "OC ascites induced a rapid (within 30 min) phosphorylation of Elk-1 in tumor cells." (PMID 23158473, 2012). "Moreover, in the presence of both CAFs and Elk1 loss, testosterone was lower in tumor tissue, whereas no change in serum testosterone was detected." (PMID 37009898, 2023). "Interestingly, ELK1 plays a role in the regulation of immune cells in tumor microenvironments." (PMID 34707096, 2021). "In addition, our finding suggested that ELK1 was up-regulated in BC tissues or cells and may play a tumor-promoting role in BC." (PMID 32670874, 2020). "Knockdown of ELK1 or LINC00839 exerted synergistic roles with Erastin or ferroptosis-inducing chemotherapeutic drug Sorafenib to enhance ferroptosis, thereby delaying tumor growth in vivo." (PMID 42135459, 2026). "Regarding tumor suppressor activity, RIGI has also been identified as a gene regulating ELK1’s expression in CC." (PMID 40862737, 2025). "Specifically, higher O-GlcNAcylation in tumor cells treated with glucosamine induced Elk1-mediated transcription of HSD3B1 and increased tumor cell viability." (PMID 37009898, 2023). "Inhibiting the expression of Elk-1 reduces the expression of PKC-α, as well as tumor migration and invasion in HCC." (PMID 36569303, 2022). "When comparing the gene expression signature of poorly differentiated (G3) tumours with the moderately differentiated (G2) ones, the downregulation of RELA, NOD1, CASP8, BCL2L1, ELK1, and IKBKB was found." (PMID 36433652, 2022). "A decrease in the levels of RELA, NOD1, CASP8, BCL2L1, ELK1, and IKBKB was identified in the poorly differentiated (G3) tumours compared with the moderately differentiated (G2) ones." (PMID 36433652, 2022). "Nude mice were injected with ELK1-knockdown or ELK1-overexpressing LUAD cells via the armpits, for evaluating the effect of ELK1 on in vivo tumor growth." (PMID 34970415, 2021).
tumor (continued). "Hsa_circ_0000512 (hsa_circ_000166) is presented earlier in this review as circRNA with an impact on tumor progression in CRC, but it has an effect on migration and invasion by another axis—miR-330-5p/ELK1 (ETS Like-1 protein Elk-1)." (PMID 34298612, 2021). "Further expression analysis also elucidated that ELK1 expression was overexpressed significantly and positively correlated with HNSC patient’s tumor grades." (PMID 32275642, 2020). "Ultimately, we identified ELK1 and STRN4 as downstream target genes for miR-873 to exert its tumor-suppressive roles." (PMID 31289617, 2019). "So we examine the expression of pElk-1, Elk-1, mTOR, HIF-1α, VEGF-A in HUVECs, which were treated by tumor supernatant and inhibitors." (PMID 30250188, 2018). "A number of TFs were significantly altered in two or more tumour types, including ZEB1, JUN, ELK1, FOXM1, while others were limited to a single type, such as FOXD1 in HNSC and FOXL1 in KIRC." (PMID 28139702, 2017). "They contribute a lot to tumor initiation and development by controlling the expression and function of tumor suppressor genes, including K-RAS, ELK1, MYO6, BCL2, ERK5 and IGF1R." (PMID 27626488, 2016). "ELK1 was found to be crucial in successful EGFR signaling, and the study also reported a positive correlation of ELK1’s and MCL1’s expression levels in BC tumors, further reinforcing the TF’s role in tumor progression and aggressiveness." (PMID 40862737, 2025). "ELK1 knockdown reverse SYTL1 suppression and leads to tumor suppression." (PMID 40862737, 2025). "Upon treatment with KCI807, that disrupts ELK1-AR interactions but not the ERK1/2-mediated phosphorylation of ELK1, the growth of the cells declined, both in castration/enzalutamide-resistant cell lines and patient-derived tumor xenografts." (PMID 40862737, 2025). "TD-19 and afatinib induce apoptosis and tumor suppression in EGFR wild-type or mutation-negative NSCLC through CIP2A inhibition, with afatinib also blocking ELK-1-mediated CIP2A transcription." (PMID 40943297, 2025). "EGFR phosphorylates ELK1 through the MEK/ERK pathway, which can activate GDH1 transcription and glutamine degradation, providing a new perspective for changes in glutamine metabolism in tumor cells." (PMID 36034789, 2022). "Transfection of Elk-1-ASO reduces cell proliferation and inhibits tumor growth in mice." (PMID 36569303, 2022). "Moreover, a decrease in the levels of RELA, NOD1, CASP8, BCL2L1, ELK1, and IKBKB was identified in poorly differentiated tumours compared to moderately differentiated tumours." (PMID 36433652, 2022). "miR-185-5p targets ROCK2, ELK1, ELK3, IGF2, RAGE, BCL2, BCL2L1, and many other genes to suppress tumor cell migration and invasion." (PMID 35223832, 2022). "In addition to E2F, several transcription factors with critical involvement in carcinogenesis and tumor progression control EZH2 transcription, such as MYC, NF-YA, STAT3, ETS, and ELK1." (PMID 34943970, 2021). "Besides, the growth of BC cells has been shown to be promoted by ELK1 and ELK3, both of which were the target genes of miR-135a and critical regulators of tumor-suppressive effects induced by miR-135a." (PMID 32670874, 2020). "Indeed, significant down-regulation of MAPK3, MAP2K2, MAPKAPK3, ELK1 and up-regulation of the phosphatase DUSP1 was found in the reprogrammed tumours." (PMID 29662623, 2018).
tumor (continued). "Immunohistochemical analyses showed that tumors from WA-treated mice exhibited higher number of tumor cells showing increased expression of phosphorylated-ERK, -RSK, -ELK1, and DR5 as compared to tumors from untreated group providing physiologic relevance to our in vitro findings." (PMID 29263422, 2017). "In non-muscle-invasive tumors, p-ELK1 positivity and tumor recurrence showed a trend toward significance [hazard ratio (HR) = 2.829, P = 0.056]." (PMID 26342199, 2015). "Patients with p-ELK1-positive non-muscle-invasive and muscle-invasive tumors had significantly higher risks for tumor recurrence and progression, respectively." (PMID 26342199, 2015). "The study also described that human tissue plasminogen activator (tPA) is a target of ELK1-mediated gene transcription, further supporting the notion of ELK1 targeting as part of anticancer therapies, given the pro-tumor roles attributed to Plasminogen activator, tissue type (tPA or PLAT)." (PMID 40862737, 2025). "In contrast, in the absence of Elk1, C4-2 xenograft tumor volume in mice treated with orchiectomy and DHEA pellet implantation (to mimic human adrenal physiology) was significantly lower in the presence of CAFs and resulted in increased progression-free survival." (PMID 37009898, 2023). "Given that the MAPK/ERK/ELK1 axis regulates BCL6 expression, we additionally explored whether BCL6 pharmacological inhibitors, such as COMP7, in combination with MEKi, could lead to more potent tumor inhibition than single-agent treatment." (PMID 36377663, 2022). "The inoculated ELK1-shRNA tumors were smaller than control-shRNA tumors, especially after day 5, although the differences in tumor size between the two groups did not narrowly reach statistical significance (P > 0.1 at days 1–8; P = 0.056 at day 9; P = 0.069 at day 10)." (PMID 26342199, 2015). "Higher CIP2A and Elk-1 expressions were found in the tumor part compared to the non-tumor part, and the expressions of CIP2A and Elk-1 were highly correlated (r=0.733, p<0.001)." (PMID 25537503, 2015). "We therefore propose the following model: more often than not, in tumor cells, the binding of MZF-1 and Elk-1 followed by clustering to the binding site of the PKCα promoter can stimulate PKCα expression." (PMID 26010542, 2015).
infection (7 papers, 2009 to 2023). The state of being infected such as from the introduction of a foreign agent such as serum, vaccine, antigenic substance or organism. "We also observed that transactivities of Elk-1 were up-regulated after infection of cagA+ H. pylori." (PMID 22536353, 2012). "This is reminiscent to what was observed for Elk1, and suggests that hPIV3 infection induces a basal activation of MAPK/ERK pathway leading to the constitutive phosphorylation of downstream targets." (PMID 19806178, 2009). "Interestingly, several transcription factors were upregulated in comparison to mock-infected samples at 24 hpi including cMyc, Elk-1, SMAD4, and cJun, suggesting that JCPyV positively upregulates MAPK-ERK-associated transcription factors during infection." (PMID 31561471, 2019). "Like hPIV3-C alone, hPIV3 infection enhanced Elk1 activity upon EGF stimulation." (PMID 19806178, 2009). "TP63, FOXA1, STAT1, ELK1, FOS, and JUN are TFs in various lung injury or infection types." (PMID 36911695, 2023). "We report that either hPIV3 infection or transient expression of hPIV3-C both increase cellular response to EGF, as assessed by Elk1 transactivation and phosphorylation levels of ERK1/2, 40S ribosomal subunit protein S6 and translation initiation factor 4E (eIF4E)." (PMID 19806178, 2009). "How the nuoG mutant infection leads to an increase in TNF-α secretion by macrophages needs to be investigated in more detail but activation of transcription factors such as ATF-2, Elk-1 and c-Jun upon JNK activation have been reported and would lead to an increase in TNF-α gene transcription." (PMID 20421951, 2010). "Interestingly, hPIV3 infection induced a significant level of Elk1 activity in the absence of EGF stimulation." (PMID 19806178, 2009).
neurodegenerative disease (6 papers, 2010 to 2025). A disorder of the central nervous system characterized by gradual and progressive loss of neural tissue and neurologic function. "The co-localization of T417+ Elk-1 with multiple neuronal inclusions suggests a common mechanism of pathogenesis and neuronal loss among distinct neurodegenerative diseases." (PMID 20126313, 2010). "We next screened human cases from three major neurodegenerative diseases to look for remarkable levels of Elk-1 and/or pElk-1 protein as well as their association with inclusions characteristic of these diseases." (PMID 20126313, 2010). "Increasing evidence supports a strong association between elevated ELK1 or p-ELK1 levels and neurodegenerative diseases including AD, and that inhibiting ELK1 may offer neuroprotective functions." (PMID 40307574, 2025). "We next assessed whether there could be an association between Elk-1 and/or pElk-1 protein with inclusions present in neurodegenerative disease." (PMID 20126313, 2010). "Alternatively, genetic variants of multiple proteins involved in the Elk-1 cell death pathway could share an association with neurodegenerative disease." (PMID 20126313, 2010). "We tested whether a specific association exists between T417+ Elk-1 and inclusions in another major neurodegenerative disease." (PMID 20126313, 2010). "Given that Elk-1 expresses within multiple brain areas and its de novo dendritic protein synthesis leads to neuronal death, we wanted to determine whether Elk-1 and/or one of its phosphoforms (pElk-1) could be involved in neuronal death associated with neurodegenerative disease." (PMID 20126313, 2010). "Furthermore, we document the co-localization of extranuclear T417+ Elk-1 with multiple types of neuronal inclusions from three major neurodegenerative diseases." (PMID 20126313, 2010). "Currently, there are no known Elk-1 single-nucleotide poIymorphisms associated with neurodegenerative disease." (PMID 20126313, 2010). "However, the exact roles and molecular mechanisms of ELK1 in neurodegenerative diseases, especially in AD, remain unclear." (PMID 40307574, 2025).
adenocarcinoma (2 papers, 2018 to 2025). A common cancer characterized by the presence of malignant glandular cells. "A significant positive correlation between miR-30c and KRAS or ELK1 was observed in the 21 lung tumor samples (P = 0.0229 and P = 0.0011, respectively) and between miR-21 and ELK1 in 160 adenocarcinoma samples from the TCGA (LUAD data set)." (PMID 29440633, 2018). "The study reports that regarding colonic adenocarcinoma, a higher percentage of ELK1 p-Thr417 positive cells indicates a well-differentiated adenocarcinoma, while both normal colon or poorly differentiated adenocarcinoma exhibit lower percentages of such cells." (PMID 40862737, 2025).
heart disease (2 papers, 2009 to 2020). "Unfortunately, the two signaling pathways have opposite effects on Elk-1 activity, making it difficult to predict how a particular heart disease will affect the transcription of Elk-1 targets." (PMID 19476647, 2009). "Our analysis suggests that Elk-1 occurrences bind preferentially in the promoters of energy and translation genes and may be relevant to understanding changes in expression during cardiac disease." (PMID 19476647, 2009).
bacterial infection (1 paper, 2017). "Upon stimulation, such as bacterial infection, the Erk-Elk1-c-Fos, Src-JNK-c-Jun, and p38 signaling pathways are activated." (PMID 28407745, 2017).
lung (1 paper, 2023). "As ELK-1 has been associated with lung carcinogenesis, a dual luciferase assay was used in the BEAS-2B cells to evaluate the ELK-1-regulated SRE activity." (PMID 36765542, 2023).